IL33 (interleukin 33)
Diseases named in the same sentence as IL33 in open-access papers (continued):
Sharing a sentence is not in itself a finding about the gene and the disease.
psoriasis (continued). "IL-33 thus enables alarmin-induced and assists in allergic as well as pseudo-allergic/neurogenic inflammation in the cutaneous environment, potentially aggravating dermatoses like AD, urticaria, and psoriasis." (PMID 33808264, 2021). "This suggests that IL-33 may be involved in the pathogenesis of inflammatory skin diseases, including psoriasis." (PMID 32214018, 2020). "In addition, levels of IL‐33 are significantly higher in synovial fluid (SF) and serum from patients with RA and psoriasis than in such samples from healthy donors." (PMID 32566227, 2020). "Usually, endothelial and epithelial cells rapidly released IL-33 after tissue injury: the same mechanism could be involved in the pathogenesis of psoriasis." (PMID 31736655, 2019). "Interestingly, TNFα, INFγ, and IL-17A, which are the main effector of the Th1/Th17 response in psoriasis pathogenesis, also resulted to stimulate the IL-33 release." (PMID 31736655, 2019). "Moreover, in Th1- and Th17-driven models of arthritis or psoriasis, IL-33 plays a proinflammatory role." (PMID 28702024, 2017). "Interestingly, IL-33 was detected in the synovium of RA patients and in lesions of patients with psoriasis." (PMID 27317338, 2016). "Indeed, IL-33 level is increased in skin lesions of patients with psoriasis and is decreased after anti-TNF-α treatment." (PMID 27317338, 2016). "Mice and humans showed strong differences in epidermal expression and regulation of IL-33, which could explain the inability of this model to reveal the pathophysiological role of IL-33 in psoriasis." (PMID 27317338, 2016). "As there is increasing evidence that IL-33 exacerbates a variety of inflammatory conditions such as bronchial inflammation, psoriasis, arthritis and ulcerative colitis, an important role for IL-33 in acute pancreatitis pathogenesis deserves active investigation." (PMID 23418608, 2013). "However, IL-33's role in psoriasis remains controversial; some studies suggest it may alleviate the condition, while others indicate it could exacerbate it." (PMID 40678000, 2025). "Therefore, we hypothesised that IL-33 could promote MC activation to regulate psoriasis development." (PMID 36894987, 2023). "Finally, IL-33 can be released by MCs after physiological stress, too, as occurs in psoriasis." (PMID 37509136, 2023). "Therefore, AHR-mediated regulation of the IL-33–IL-37 axis may lead to new therapeutic strategies for the treatment of AD and psoriasis." (PMID 37834081, 2023). "Therefore, increased expression of IL-1α and other cytokines of its family, such as IL-33, in the intestinal lumen of patients with psoriasis may be the link between the gut inflammation accompanying this dermatosis and skin lesions." (PMID 37509136, 2023). "Thus, we aimed to compare IMQ-induced psoriasis-like skin inflammation in WT and IL-33-/- mice." (PMID 27317338, 2016). "As RA, psoriasis is a chronic inflammatory disease, and IL-33 may have a role in its pathogenesis." (PMID 27317338, 2016). "Despite the fact that IL-21 and IL-33 have been implicated in psoriasis pathogenesis, we could not find any difference in the production of these cytokines between lesional and unaffected skin of psoriasis patients (data not shown)." (PMID 23468834, 2013). "Our cytokine analysis showed elevated levels of IL-6, IL-18, and IL-33, demonstrating a complex network of interactions in TNF inhibitor-induced psoriasis." (PMID 40678000, 2025). "Against this background, this review outlines the latest findings on the regulatory mechanisms of the IL-33–IL-37 axis by AHR in AD and psoriasis." (PMID 37834081, 2023). "The aim of the study was to investigate expression of IL-33 and its receptor, ST2, in psoriasis, and the effects of the active form of vitamin D (1,25(OH)2D3) on their expression in skin cells." (PMID 34884710, 2021).
psoriasis (continued). "Although the neutralization of IL-1RAcP affects the pathway induced by IL-1α, IL-1β and IL-33, its administration has positive effects in the control of the inflammation in OVA-induced allergic airway inflammation and Imiquimod-induced psoriasis." (PMID 34887860, 2021). "Nevertheless, previous studies have demonstrated a detrimental role of IL-33/ST2 axis in RA, scleroderma, SLE, psoriasis, and gout." (PMID 34589505, 2021). "The expression levels of both IL-33 and ST2 are up-regulated in psoriasis, likely as a consequence of keratinocyte damage." (PMID 33488605, 2020). "The analysis of skin biopsies even suggests that the gene expression of IL-33 along with histidine decarboxylase (HDC), an indicator of mast cell presence, is considerably increased in both affected and unaffected psoriasis skin." (PMID 31736655, 2019). "Proinflammatory cytokines, such as IL-33, osteopontin (OPN), IL-17, and TNF-α, are involved in both psoriasis and PsA pathogenesis as well as in bone homeostasis." (PMID 31659208, 2019). "Taken together, our investigation demonstrated the novel mechanism wherein the alarmins IL-33 and TSLP exacerbate NET formation that may drive enhanced inflammation and oxidative stress in psoriasis." (PMID 41596128, 2026). "By contrast, another study found that a mouse model of imiquimod-induced psoriasis that lacked epidermis-specific IL-33 displayed much milder psoriatic lesions than control mice." (PMID 38666958, 2024). "In a mouse model of imiquimod-induced psoriasis, mice lacking epidermis-specific IL-33 developed milder psoriatic skin lesions than control mice." (PMID 37834081, 2023). "After release, IL-33 can diffuse from the epidermis into the dermis, triggering ST2-positive cells, including MCs, since the gene expression levels of IL-33 and histidine decarboxylase are significantly increased in the skin of patients with psoriasis." (PMID 36405690, 2022). "On the other hand, an increase in IL-33 is observed in skin lesions of psoriasis while no increase is observed in the serum." (PMID 35432341, 2022). "The expression and the release of IL-33 and HSP90 are upregulated in psoriasis patients." (PMID 36142767, 2022). "The co-administration of IL-33 with the peptide substance P (SP) significantly increases the expression and secretion of TNF and VEGF in MCs, further promoting angiogenesis and increasing inflammation in psoriasis." (PMID 36405690, 2022). "IL-33 can be released by MCs after physiological stress, as occurs in psoriasis—a non-allergic, hyper-proliferative inflammatory skin disease with an important neurogenic component." (PMID 34360845, 2021). "Our results indicate that there is significant dysregulation of IL-33 and ST2 expression in psoriasis, which may contribute to its pathogenesis." (PMID 34884710, 2021). "In psoriasis there can be an augmentation of neurotransmitters, such as substance P (SP), which induces VEGF in human mast cells—an effect that leads to increased IL-33 and inflammation." (PMID 34360845, 2021). "In fact, IL-1 has the ability to stimulate MCs to produce IL-6, TNF, and IL-33 without degranulation, building a powerful proinflammatory network—an effect that increases with stress, which exacerbates psoriasis." (PMID 34360845, 2021). "HMGB1, IL-33, S100A7, and S100A12 were chosen as the most promising alarmins according to the literature, because they were reported to be elevated in various autoimmune diseases, yet their role in pathophysiology of psoriasis is still unclear." (PMID 32377165, 2020). "Despite its expression in the synovium of arthritic mice and normal keratinocytes, IL-33 is not required for CIA development in arthritis or psoriasis." (PMID 27317338, 2016). "Arthritis and psoriasis developed independent of IL-33 expression, despite IL-33 promotor activation within the synovium during the course of arthritis and IL-33 expression in skin." (PMID 27317338, 2016).
psoriasis (continued). "We also assessed functionality of the T cells by evaluating the secretion of several inflammatory cytokines (IL-17A, IFN-gamma, IL-2, IL-33, TNF-alpha, IL-21, IL-22, and IL-27), from cell-sorted purified CD4+ and CD8+ T cells isolated from lesional and unaffected skin biopsies of psoriasis patients." (PMID 23468834, 2013). "Mechanistically, IL-33 may impair Th17 differentiation via suppression of RORγt (RORC) and STAT3 signalling while promoting Treg expansion, rebalancing immune homeostasis in psoriasis." (PMID 40681996, 2025). "Interestingly, there is a distinct pattern in the expression of IL-33 and ST2 in psoriasis." (PMID 40681996, 2025). "While Th2 cytokines such as IL-4, IL-13, IL-33, and TSLP dominated the inflammatory landscape in AD and bullous pemphigoid, Th1 and Th17 immune responses, primarily mediated by IFN-γ and IL-17, characterized psoriasis, lichen planus, and specific forms of GvHD." (PMID 41479908, 2025). "Remarkably, the role of IL-33 in psoriasis should not be underscored." (PMID 38239345, 2023). "Because MAB-hR3 disrupts the recruitment of IL-1RAcP, other inflammatory signals mediated by IL-1α, IL-1β and IL-33 were also disrupted in vitro and in vivo models of local and systemic inflammation models in mice such as peritonitis, OVA-induced airway allergy and Imiquimod-induced psoriasis." (PMID 34887860, 2021). "The alarmins HMGB1, IL-33, S100A7, and S100A12 were significantly elevated in the serum of patients, which states the hypothesis that they play specific roles in the immunopathology of psoriasis." (PMID 32377165, 2020). "In these cases, the authors speculated that IL-33 skin increase was not related to psoriasis development." (PMID 31736655, 2019). "However, the serum level of IL-33 does not correlate with psoriasis severity." (PMID 38666958, 2024). "The epithelium-derived cytokines, namely TSLP, IL-25 and IL-33 represent a new target for future therapies, especially in terms of itch control and, possibly, side-effects minimization, but not enough studies, especially in psoriasis, have been conducted in this direction." (PMID 34944487, 2021). "In contrast with that of IL-33, the ACE2 expression was not enhanced by IL-17, a cytokine closely relevant to the pathophysiology of psoriasis." (PMID 35625919, 2022). "Even though IL-33 is expressed within the synovium of arthritic mice, CIA develops independently of IL-33, and in psoriasis, as well, its absence does not affect the T cell shift toward Th1, Th17, or Treg subpopulations." (PMID 27317338, 2016).
pulmonary fibrosis (73 papers, 2008 to 2025). Chronic progressive interstitial lung disorder characterized by the replacement of the lung tissue by connective tissue, leading to progressive dyspnea, respiratory failure, or right heart failure. "IL-33 can promote ST2-associated pulmonary fibrosis by inducing the alternating activation of mouse macrophages and innate lymphoid cells." (PMID 39925809, 2025). "Our results demonstrate that acute neutrophilic pulmonary inflammation leads to the development of an IL-33/ST2-dependent lung fibrosis associated with the production of M2-like polarization." (PMID 29988569, 2018). "Furthermore, adoptive ILC2 transfer into recipient mice enhances lung fibrosis, whereas blocking IL-33 or ST2 deficiency diminish fibrosis." (PMID 30405626, 2018). "Moreover, IL-33 has been implicated in pulmonary fibrosis associated with systemic sclerosis (SSc)." (PMID 39301028, 2024). "Previous studies have suggested that activation of the IL-33/ST2 axis as well as elevated expression of the full-length IL-33 precursor acting in an ST2-independent fashion both contribute to pulmonary fibrosis." (PMID 41465219, 2025). "IL-13 with IL-33 synergistically stimulates the polarization of M2 macrophages that play an important role during the late pulmonary fibrosis phase." (PMID 40191199, 2025). "The relationship between IL-33 and lung fibrosis has been reported in mice, in which fibroblast-derived IL-33 is important in fibrosis." (PMID 40059822, 2025). "LncRNA MIR205HG was identified as a prognostic factor of idiopathic pulmonary fibrosis and stabilized IL33 via the interaction of their Alu elements in pulmonary epithelium." (PMID 40059822, 2025). "In conclusion, the relationship between IL-33 and pulmonary fibrosis is intricate, highlighting it as a promising area for further research into the mechanisms and treatment strategies for PF in the future." (PMID 39301028, 2024). "In the bleomycin‐induced lung fibrosis mouse model, airway epithelial cells and alveolar macrophages produce IL‐33 to exacerbate lung fibrosis." (PMID 39654685, 2024). "Two methods of ILC2 depletion were employed to determine the contribution of ILC2s in HPS-lung fibrosis: an IL-33 siRNA to knock down the expression of IL-33 and Rorafl/flIL-7Rcre mice, in which ILC2s are depleted." (PMID 39405112, 2024). "IL-33 has been demonstrated to serologically correlate with the degree of skin thickness, pulmonary fibrosis, and early disease state." (PMID 39408800, 2024). "In the bleomycin mouse model of lung fibrosis, ILC2s are activated by an IL-33/ST2–dependent mechanism and promote fibroblast activation." (PMID 39405112, 2024). "Recent studies have suggested that IL-33 plays a role in the progression of pulmonary fibrosis, contributing to local inflammation and the formation of fibrotic tissue." (PMID 39301028, 2024). "utilized a mouse model of bleomycin (BLM)-induced pulmonary fibrosis and evaluated the fibrotic potential of the IL-33-mediated ST2 signaling pathway using a therapeutic dose of ST2-Fc fusion protein." (PMID 39301028, 2024). "Their findings demonstrated that mice lacking USP38 displayed more severe pulmonary fibrosis and IL-33-associated lung inflammation following exposure to bleomycin, further solidifying the intricate connection between IL-33 and pulmonary fibrosis." (PMID 39301028, 2024). "Xie and colleagues recently showed that BM-MSC-Exo-sourced miR-214 inhibited progression of bleomycin-induced pulmonary fibrosis by suppressing the IL-33/ST2 axis in fibrotic lungs." (PMID 38673961, 2024). "Recent research has demonstrated elevated levels of IL-33 in SSc patients, with correlations observed between IL-33 levels and the severity of skin sclerosis and pulmonary fibrosis." (PMID 39301028, 2024). "Previously, we demonstrated that IL-33 released from epithelial cells induced macrophage activation and contributed to pulmonary fibrosis." (PMID 37523510, 2023).
pulmonary fibrosis (continued). "In vivo, the fibrotic potential of IL-33:ST2 signalling was assessed using a murine model of bleomycin (BLM)-induced pulmonary fibrosis and therapeutic dosing with an ST2-Fc fusion protein." (PMID 36949463, 2023). "Mature IL-33 was shown, in bleomycin-driven pulmonary fibrosis, to promote a Th2 cytokine profibrotic environment." (PMID 36403186, 2023). "IL‐33/ST2 pathway contributed to fibroblast activation to promote lung fibrosis by recruiting BM‐derived ILC2s." (PMID 36082495, 2022). "In summary, the current studies have established that IL-33 can play a pivotal role in promoting the process of pulmonary fibrosis." (PMID 35634336, 2022). "For instance, the IL-33/Akt1 pathway regulates pulmonary fibrosis by enhancing the production of the profibrotic cytokine IL-13 by macrophages." (PMID 36362440, 2022). "In this review, we have summarized the structure and basic functions of IL-33, its possible function in immune regulation, and its role in pulmonary fibrosis as well as in lung cancer." (PMID 35634336, 2022). "sST2 attenuated lung fibrosis by blocking IL‐33/STL2 axis and down‐regulating proinflammatory and profibrotic mediators." (PMID 36082495, 2022). "The important roles and mechanisms of IL‐25/IL‐33/TSLP are mainly elucidated by experimental murine lung fibrosis model induced by BLM or S. mansoni eggs." (PMID 36082495, 2022). "Animal models provide evidence that IL-33 is able to induce both cutaneous and pulmonary fibrosis via increased IL-13 and in SSc patients the levels of IL-33 correlate with skin fibrosis." (PMID 35252259, 2022). "By contrast, mature (m)‐IL‐33 potentiates lung fibrosis by recruiting ST2L+M2 macrophages and ST2L+ILC2 to enlarge type 2 immunity." (PMID 36082495, 2022). "IL-33 promotes initiation and progression of pulmonary fibrosis by M2-like polarization of macrophages through ST2 signaling." (PMID 35046838, 2021). "Numerous studies have also demonstrated a pro-fibrotic role for IL-33 in driving excessive repair and remodelling pathways in pulmonary fibrosis." (PMID 34685744, 2021). "BLM administration induces IL-33 production in murine pulmonary macrophages, which recruits and activates immune cells and finally promotes pulmonary fibrosis." (PMID 32390869, 2020). "In BLM-induced pulmonary fibrosis model, ST2 deficiency, anti–IL-33 antibody treatment, or alveolar macrophage depletion attenuated BLM-induced lung inflammation and fibrosis." (PMID 32390869, 2020). "In vivo, IL-33 expression in lung fibroblasts is increased in mice with bleomycin-induced pulmonary fibrosis, and in patients with idiopathic pulmonary fibrosis." (PMID 32903501, 2020). "The current results also showed that IL-33 expression was increased in serum during BLM-induced lung fibrosis, consistent with the findings of previous studies." (PMID 31049028, 2019). "When we performed a tissue analysis of IL-33 mice production with comorbidity, it also showed a significant increase in relation to bleomycin-induced pulmonary fibrosis." (PMID 31765381, 2019). "The expression of IL-33 mRNA is reported to increase in the primary pulmonary fibroblasts from patients with SSc-ILD as well as in those from patients with idiopathic pulmonary fibrosis (IPF)." (PMID 30498500, 2018). "Our data showed that antofine can modulate the expression of lung fibrosis‐related cytokines such as IL‐10 and IL‐33." (PMID 28805975, 2017). "Despite the relations of the pulmonary fibrosis with IL-25, IL-33, and TSLP, the clinical implications of these cytokine remain poorly defined due to the small number of subjects (less than 15) examined in the previous studies." (PMID 28202030, 2017). "In this context, an interplay between ILC, macrophages, and cells of the adaptive immune system was shown to participate—together with IL-13, IL-25, and IL-33—in the pathogenesis of BLM-induced pulmonary fibrosis in mice." (PMID 28018357, 2016).